LINC01288 (long independently transcribed non-coding RNA 1288)
Synonyms: TCONS_00014671
Gene: Long non-coding RNA gene on chromosome 8 (34,784,028 to 34,865,364, forward strand). Ensembl gene ENSG00000254344.
Diseases named in the same sentence as LINC01288 in open-access papers:
LINC01288 is named in the same sentence as 1 disease in open-access papers, as found by Europe PMC text mining. Sharing a sentence is not in itself a finding about the gene and the disease.
LINC01288 shares sentences with these, for which no sentence is quoted: tumour (1 paper).